SYT1 (synaptotagmin 1)
Diseases named in the same sentence as SYT1 in open-access papers (continued):
Sharing a sentence is not in itself a finding about the gene and the disease.
glioma (8 papers, 2017 to 2025). A benign or malignant brain and spinal cord tumor that arises from glial cells (astrocytes, oligodendrocytes, ependymal cells). "Syt1 has been reported to be associated with oxidative stress regulation in glioma, neuron, and diabetic encephalopathy, but direct evidence is lacking." (PMID 39865120, 2025). "In the immunoblot experiment using materials pulled down from the C6 glioma cell cytosol fraction and anti-Syt-1 IgG in a Ca2+-dependent manner, a single positive band was detected at 40 kDa, corresponding to p40 Syt-1, which is deficient of the membrane-spanning domain of p65 Syt-1." (PMID 37371039, 2023). "For example, Grade 1→2 gliomas show upregulation of exocytic SNARE proteins (SYT-1, Syntaxin-1) and neurotransmitter transporters, while dynamin-dependent fission is suppressed." (PMID 40705199, 2025). "The specificity was observed in the finding that large amounts of S100A13 and Syt-1 were lost due to serum deprivation in C6 glioma cells pretreated with heat-inactivated BoNT1." (PMID 37371039, 2023). "The LASSO regression model was constructed to screen the molecular models related to glioma prognosis, which were composed of SYT1, CREB3L3, ITPR1, RASGRF2, PDX1, and RASGRF1." (PMID 37090987, 2023). "Among the core genes, the expression levels of GABRD and SYT1 were closely related to the survival time of glioma patients." (PMID 33718116, 2020). "The oxidative stress imbalance in glioma was accompanied by down-regulation of Syt1 mRNA." (PMID 39865120, 2025). "Interestingly, the imbalance of oxidative stress-related pathways was also exhibited in glioma tissues, and the expression of SYT1, CREB3L3, ITPR1, RASGRF1, RASGRF2, and PDX1 were significantly different from that of para-cancerous tissues." (PMID 37090987, 2023). "Prothymosin alpha (ProTα) and S100A13 are released from C6 glioma cells under serum-free conditions via membrane tethering mediated by Ca2+-dependent interactions between S100A13 and p40 synaptotagmin-1 (Syt-1), which is further associated with plasma membrane syntaxin-1 (Stx-1)." (PMID 33807671, 2021). "In addition, GABRD and SYT1 are implicated in gliomagenesis, and all other core genes, with the exception of OPALIN, have been reported to play a role in tumor-related diseases, including glioma." (PMID 33718116, 2020). "Nomogram and calibration curves further confirmed that the prognostic model composed of SYT1, CREB3L3, ITPR1, RASGRF2, PDX1, and RASGRF1 has good stability and potential application value for poor prognosis in patients with glioma." (PMID 37090987, 2023). "In this experiment both intracellular signals of synaptotagmin-1 (Syt-1) and S100A13 were reduced in C6 glioma cells cultured under serum-free conditions following normal goat antibody delivery." (PMID 33807671, 2021). "It has been proposed that glioma CSCs express differentiation markers similar to those in normal glia and neurons, such as of oligodendrocytes (ASCL1, OLIG2 and DLL3), astrocytes (GFAP), neurons (β-tubulin III, SYT1 and SLC12A5), and markers of inflamed astroglial cells (SERPINE1, TGFB1 and RELB)." (PMID 31661894, 2019).
cognitive decline (7 papers, 2016 to 2025). "This study showed a link between synaptic plasticity-related genes Arc and Syt1 expression and age-associated cognitive decline induced by prenatal inflammation combined with long-term EE." (PMID 35574247, 2022). "With regard to behavioral aspects, prenatal inflammation induced the overexpression of Arc and Syt1 mRNA in the hippocampus and led to a series of spatial learning and memory deficits, including the acceleration of age-associated cognitive decline." (PMID 35574247, 2022). "We demonstrated that exposure to an EE from adolescence could improve age-associated cognitive decline and facilitate spatial learning and memory by downregulating the expression of Arc and Syt1 in the hippocampus." (PMID 35574247, 2022). "A mounting body of evidence suggests that prenatal inflammation may enhance the rate of age-associated cognitive decline and may involve aberrant amounts of synaptic proteins in the hippocampus, including synaptotagmin-1 (Syt1) and activity-regulated cytoskeleton-associated protein (Arc)." (PMID 35574247, 2022). "However, although we have shown that the provision of EE from adolescence is beneficial for age-associated cognitive decline, few studies have investigated whether EE can affect the expression of the synaptic proteins Arc and Syt1 in the hippocampus induced by prenatal inflammation." (PMID 35574247, 2022). "Synaptotagmin-1 in cerebrospinal fluid is a candidate Alzheimer biomarker for synaptic dysfunction that also may correlate with cognitive decline." (PMID 27716408, 2016). "Further studies are therefore needed to investigate whether synaptotagmin-1 in CSF could be used for assessment of the future rate of cognitive decline." (PMID 27716408, 2016). "Similarly, synaptotagmin-1 (SYT-1) may serve as marker of progressive cognitive decline, since it shows higher levels in MCI patients progressing to AD." (PMID 41373799, 2025).
dementia (7 papers, 2016 to 2026). Loss of intellectual abilities interfering with an individual's social and occupational functions. "Among the top 20 proteins in the brain aging clock, those associated with at least two dementia phenotypes included glial fibrillary acidic protein (GFAP), neurofilament light chain polypeptide (NEFL), brevican (BCAN), kallikrein-6 (KLK6) and synaptotagmin-1 (SYT1)." (PMID 41299092, 2026). "There was a significant interaction with group for SYT1, NPTX1, NPTX2, and NPTX-R; slopes of AD dementia patients (st.B[SE] –0.15[0.05], –0.11[0.04], –0.13 [0.04], and –0.10[0.04] respectively) differed from those of SCD/MCI-A– subjects." (PMID 39121126, 2024). "Synaptic proteins such as synaptosomal-associated protein 25 (SNAP-25) and synaptotagmin-1 (SYT1) were found to be significantly increased in the CSF of AD dementia and prodromal AD patients; however, SNAP-25 and SYT1 were specified to decline in cortical areas." (PMID 32708853, 2020).
colon cancer (6 papers, 2019 to 2024). "Altogether, these conventions signify that miR-34a and SYT1 are essential elements for the proliferation of colon cancer." (PMID 38725047, 2024). "Evidence that miR-34a directly targets the 3’ untranslated region (UTR) of SYT1 suggested that miR-34a affected SYT1 in colon cancer." (PMID 38725047, 2024). "When SYT1 was deactivated, execution of cell migration, invasion, and proliferation was severely restricted, along with raised cell death, indicating that SYT1 possibly serves as an oncogene in colon cancer." (PMID 38725047, 2024). "In line with this, Slug and Vimentin was also downregulated in tumors in situ of SYT1 overexpression group mice, suggesting that SYT1 suppressed the colon cancer cells metastasis." (PMID 37958455, 2023). "In a recent study, downregulation of SYT1 significantly suppressed the proliferation, invasion, and migration of colon cancer cells, but induced cell apoptosis." (PMID 36004367, 2022). "The knockdown of SYT1 markedly inhibits colon cancer cell proliferation, migration, and invasion, and induces cell apoptosis, indicating that SYT1 may function as an oncogene in colon cancer." (PMID 36352089, 2022). "miR-34a was recently shown to target SYT1 in human colon cancer." (PMID 34722255, 2021). "miR-34a was recently shown to increase apoptosis by targeting SYT1 in human colon cancer (CC)." (PMID 34722255, 2021). "We further confirm that SYT1 overexpression suppresses CRC metastasis both in vivo and in vitro using mouse CRC xenograft metastasis model and colon cancer cells." (PMID 37958455, 2023).
Anxiety (5 papers, 2020 to 2025). Intense feelings of nervousness, tension, or panic often arise in response to interpersonal stresses. "Correlation between the performance in the anxiety/cognition-related tasks and hippocampal mRNA levels of BDNF and Syt-1 [r (p)]." (PMID 36570704, 2022). "None of the anxiety-related indicators correlated with the hippocampal protein levels of BDNF and Syt-1 in the OF and EPM test (P < 0.05)." (PMID 36570704, 2022). "Most of the anxiety-related indicators were not correlated with the hippocampal mRNA levels of BFNF and Syt-1 in the OF and EPM tests." (PMID 36570704, 2022).
glioblastoma (5 papers, 2019 to 2024). The most malignant astrocytic tumor (WHO grade IV). "A later study further analyzed more glioblastoma and normal brain tissue samples from the TCGA and GEO databases, and the results showed that SYT1 is a core gene among 552 differentially expressed genes." (PMID 33718116, 2020). "Although the roles of SYT1 have been demonstrated in a variety of malignancies, such as glioblastoma and HNSCC, the potential role of SYT1 in CRC remains unclear." (PMID 37958455, 2023). "Glioblastoma cases belonging to the neural subtype were characterized by the expression of genes well-known as neuron markers such as GABRA1, neurofilament light chain (NEFL), synaptotagmin-1 (SYT1) and solute carrier family 12 member 5 (SLC12A5)." (PMID 33324155, 2020).
Intellectual disability (5 papers, 2018 to 2025). "Previously reported missense SYT1 variants in the C2B domain are associated with severe intellectual disability, movement disorders, behavioral disturbances, and electroencephalogram abnormalities." (PMID 35101335, 2022). "Pathogenic missense variants in the essential synaptic vesicle protein synaptotagmin-1 (SYT1) cause a neurodevelopmental disorder characterised by motor delay and intellectual disability, hyperkinetic movement disorder, episodic agitation, and visual impairments." (PMID 39481209, 2024). "Mutations in PRRT2, which influences Ca2+-dependent synchronous release via interaction with SYT1, lead to benign infantile familial seizures, paroxysmal movement disorders and intellectual disability." (PMID 30107533, 2018).
memory impairment (5 papers, 2018 to 2023). "Our previous study showed that MSD significantly downregulated brain-derived neurotrophic factor (BDNF) expression and upregulated synaptotagmin-1 (Syt-1) expression in the hippocampus, which was associated with spatial learning and memory impairment detected in the MWM." (PMID 37168717, 2023). "Decrease in the rate or absence of SYN, SNAP-25, and SYT1 mRNAs ends to learning and memory impairment." (PMID 36588719, 2022).
schizophrenia (5 papers, 2010 to 2023). A major psychotic disorder characterized by abnormalities in the perception or expression of reality. "The paper shows increase of SYT1 mRNA in younger schizophrenia patients group, while it shows decrease of SYT1 mRNA in older schizophrenia patients." (PMID 20098743, 2010). "For example, miR-153 regulates Snap25, Vamp2, Snca, Trak2, Bsn and Pclo genes at the mRNA level; miR-137 inhibits complexin-1, Nsf and Syt1 in mouse model of schizophrenia; miR-34c targets VAMP-2 and miR-135a binds the complexin-1 and complexin-2 genes in the amygdala." (PMID 32252776, 2020). "We then focused on three genes; Myristoylated alanine-rich protein kinase C substrate (MARCKS), Phospholipase C beta 4 (PLCB4) and Synaptotagmin 1 (SYT1), because an accumulating number of reports point to the involvement of impaired neural transmission in the schizophrenia pathology." (PMID 20098743, 2010). "Interestingly, a previous report suggests the alteration of SYT1 in schizophrenia patients." (PMID 20098743, 2010).
autism (4 papers, 2019 to 2025). Persistent deficits in social interaction and communication and interaction as well as a markedly restricted repertoire of activity and interest as well as repetitive patterns of behavior. "SYT1 alterations have been associated with neurologic disorders, and autism." (PMID 40779003, 2025).
developmental delay (4 papers, 2022 to 2026). "In this study we identified a missense de novo mutation at a highly conserved location in Syt1 (P401L) in a patient with developmental delay and ASD symptoms." (PMID 38321119, 2024). "De novo mutations in synaptotagmin-1 (syt1) cause a rare neurodevelopmental disorder, manifesting in global developmental delay, ophthalmic abnormalities, infantile hypotonia, facial dysmorphisms, absent speech, EEG abnormalities, and hyperkinetic movements, ranging from moderate to severe." (PMID 41756855, 2026). "SYT1-associated neurodevelopmental disorder presents with individually nonspecific features, but may be suspected when neonatal hypotonia, developmental delay, abnormal eye physiology, movement disorders, and EEG abnormalities are present in any combination." (PMID 35101335, 2022). "Heterozygous SYT1 variants cause a neurodevelopmental disorder with global developmental delay and other abnormalities, but without seizures and brain anomalies." (PMID 39085459, 2024).
hypothyroidism (4 papers, 2014 to 2022). Abnormally low levels of thyroid hormone. "By the administration of T4, it was observed that hypothyroidism-induced downregulation of the syt-1 protein and upregulation of the SNAP-25 protein was restored in the hippocampus." (PMID 25371181, 2015). "Using immunohistochemical analysis, the results indicated that the effects of adult-onset hypothyroidism on syt-1 and SNAP-25 are different, although these proteins are required for neurotransmitter exocytosis." (PMID 25371181, 2015). "However, it has been hypothesized that the reduced expression of syt-1 may be due to the reduced expression of TH receptors as well as a decrease in the number and/or volume of neurons in the hippocampus associated with hypothyroidism, considering it is an abundant constituent of synaptic vesicles." (PMID 25371181, 2015). "In conclusion, this study demonstrated that hypothyroidism induces alterations of hippocampal Ach level and AChE activity, as well as syt-1 and SNAP-25 expression, in adult rats." (PMID 25371181, 2015). "Significantly, co-administration of T4 and DON led to normalization of the syt-1 and SNAP-25 levels, suggesting that DON treatment may facilitate the recovery of synaptic protein impairment induced by hypothyroidism." (PMID 25371181, 2015). "Therefore, in this study, we have investigated the concentration of ACh and the activity of AChE, as well as the expression levels of syt-1 and SNAP-25 in the hippocampus of adult-onset hypothyroidism." (PMID 25371181, 2015).
breast carcinoma (3 papers, 2019 to 2021). "We subsequently identified individual TEs within the promoters of breast cancer-associated genes and confirmed that TEs located upstream of SYT1, UCA1, AK4 and PSAT1 contributed promoter activity in TNBC cell lines." (PMID 31061680, 2019). "Nonetheless, SYT1 expression is likely mediated by the L1PA2-SYT1 transposon in the context of breast cancer cell lines." (PMID 31061680, 2019).
Lambert-Eaton myasthenic syndrome (3 papers, 2012 to 2019). Lambert-Eaton myasthenic syndrome (LEMS) is an autoimmune, presynaptic disorder of neuromuscular transmission characterized by fluctuating muscle weakness and autonomic dysfunction frequently associated with small-cell lung cancer (SCLC). "In patients carrying SYT1 mutations, CMAP amplitudes may be initially low but may markedly increase after forced exercise, like in Lambert-Eaton myasthenic syndrome." (PMID 30808424, 2019).
colorectal cancer (2 papers, 2023 to 2025). A primary or metastatic malignant neoplasm that affects the colon or rectum. "It is well known that the MAPK signaling pathway plays a vital role in the progression of cardiac hypertrophy, and SYT1 has been confirmed to regulate the MAPK signaling pathway in colorectal cancer." (PMID 40279007, 2025). "However, the role of SYT1 in colorectal cancer remains an enigma." (PMID 37958455, 2023). "Although synaptotagmin 1 (SYT1) has been identified participating in a variety of cancers, its role in colorectal cancer (CRC) remains an enigma." (PMID 37958455, 2023).
diabetes (2 papers, 2021 to 2023). "In this study, we demonstrated that tirzepatide reversed PSD95 and SYT1 loss in the hippocampus of diabetics, suggest that tirzepatide’s ability to restore memory is related to its effect on synaptic function." (PMID 37701028, 2023).
head and neck squamous cell carcinoma (2 papers, 2023 to 2025). A squamous cell carcinoma that arises from any of the following anatomic sites: lip and oral cavity, nasal cavity, paranasal sinuses, pharynx, larynx, and salivary glands. "Further studies have demonstrated that Syt1 is expressed in some tumor tissues and tumor cells including thyroid cancer tissues, head and neck squamous cell carcinoma (HNSCC) tissues." (PMID 39865120, 2025).
liver cancer (2 papers, 2023 to 2024). An epithelial or non-epithelial malignant neoplasm that arises from the liver. "Studies have shown that cytoplasmic proteins interact with SYT1 on the endoplasmic reticulum and then are spatially localized in the SEC22B + vesicles of liver cancer cells." (PMID 38393698, 2024).
lung carcinoma (2 papers, 2019 to 2022). "Additionally, the LINE-1 integrated region into SYT1 acts as an alternative promoter and upregulates SYT1 expression, which over-activates the regulatory mechanism in membrane interactions in lung cancer." (PMID 36142830, 2022).
neuroblastoma (2 papers, 2017 to 2022). Neuroblastoma (NB) is the most common solid, extracranial childhood tumor. "We therefore tested this neuroblastoma cell line for the presence of BoNT/B receptors – synaptotagmin 1 and the ganglioside GT1b." (PMID 29170639, 2017). "The levels of synaptotagmin-1, a key protein that is involved in fusion and endocytosis, also remained unchanged when exposed DA-induced oligomeric α-synuclein aggregates in human neuroblastoma SH-SY5Y cells." (PMID 36139038, 2022).
somatotroph adenomas (2 papers, 2019 to 2022). "RT-PCR result showed the mRNA levels of PTTG1 and SYT1 in somatotroph adenomas samples were higher than those in healthy pituitary glands." (PMID 31391849, 2019). "IHC was used to analyze the H-scores of PTTG1 and SYT1 for 62 somatotroph adenomas and 6 healthy pituitary samples." (PMID 31391849, 2019). "PTTG1 and SYT1 were the target mRNAs of miR-423-5p, and transcriptomics and proteomics profile both indicated the high expression of PTTG1 and SYT1 in somatotroph adenomas." (PMID 31391849, 2019). "H-Scores were 223.1 ± 34.7 for PTTG1 and 163.4 ± 42.3 for SYT1 in 62 somatotroph adenomas specimens and 84.2 ± 21.3 for PTTG1 and 47.4 ± 17.2 for SYT1 in 10 healthy pituitary specimens by IHC." (PMID 31391849, 2019). "In our study, mRNA and proteomics profiling showed higher expression of SYT1 at the mRNA and protein levels in somatotroph adenomas than healthy pituitary glands." (PMID 31391849, 2019). "Integrating the transcriptomics and proteomics profiling of somatotroph adenomas, we revealed PTTG1 and SYT1 were differently expressed at the protein and mRNA levels between somatotroph adenomas and healthy pituitary samples; these two genes were the targets of miRNA-423-5p." (PMID 31391849, 2019). "Proteomics data indicated the protein levels were 2.16-fold higher for SYT1 and 4.96-fold higher for PTTG1 in somatotroph adenomas than in healthy pituitary glands." (PMID 31391849, 2019). "H-scores were 223.1 ± 34.7 for PTTG1 and 163.4 ± 42.3 for SYT1 in 62 somatotroph adenomas specimens and 84.2 ± 21.3 for PTTG1 and 47.4 ± 17.2 for SYT1 in 6 healthy pituitary specimens by IHC." (PMID 31391849, 2019). "Western blots showed protein levels of 0.43 ± 0.15-fold for SYT1 and 0.23 ± 0.14-fold for PTTG1 in somatotroph adenomas compared to the control group and restored to 0.78 ± 0.3-fold and 0.94 ± 0.15-fold in miR-423-5p+inhibitor group (p< 0.05)." (PMID 31391849, 2019). "Microarray analysis showed that mRNA levels were 12.17-fold higher for SYT1 and 2.41-fold higher for PTTG1 in somatotroph adenomas than in healthy pituitary glands." (PMID 31391849, 2019).